CGAS (cyclic GMP-AMP synthase)
Diseases named in the same sentence as CGAS in open-access papers (continued):
Sharing a sentence is not in itself a finding about the gene and the disease.
atherosclerosis (28 papers, 2020 to 2026). A disease characterized by the build-up of fatty material and calcium deposition in the arterial wall resulting in partial or complete occlusion of the arterial lumen. "The cGAS-STING pathway promotes atherosclerosis and cardiac injury and inhibits angiogenesis, causing inflammatory reactions in endothelial cells and macrophages." (PMID 38164186, 2024). "Meanwhile, RNA sequencing (RNA-seq) analysis of the underlying mechanisms of atherosclerosis in RAW264.7 macrophages treated with cGAS inhibition was conducted." (PMID 33589571, 2021). "A total of 275 DEGs associated with atherosclerosis were found when cGAS was inhibited." (PMID 33589571, 2021). "Exploring the role of cGAS in atherosclerosis and the possible underlying mechanisms may provide a new potential therapeutic target for atherosclerosis." (PMID 33589571, 2021). "In order to understand whether cGAS inhibition changes expression of the genes involved in modulating atherosclerosis, we identified DEGs in cGAS inhibition probably linked to atherosclerosis according to research published in the PubMed database." (PMID 33589571, 2021). "Dysregulation of glucose–lipid metabolism affects atherosclerosis and cardiovascular outcomes through the endogenous cGAS‐STING signaling pathway." (PMID 41585951, 2026). "The experimental observations outlined here demonstrate the pivotal role of the cGAS-STING pathway in the development of atherosclerosis." (PMID 40076955, 2025). "The cGAS-STING pathway has emerged as a significant player in the developmentand progression of atherosclerosis, a chronic inflammatory disease characterizedby the accumulation of plaque in the arterial wall." (PMID 39076568, 2024). "The dysregulation of the cGAS-STING pathway in atherosclerosis suggests itsinvolvement in multiple stages of plaque development and progression." (PMID 39076568, 2024). "In a study on atherosclerosis, the induction of the inflammatory response by activation of cGAS promoted the initiation and development of atherosclerosis." (PMID 37354378, 2023). "In macrophages, this activates cyclic GMP-AMP synthase (cGAS) and induces a type I interferon response, potentially promoting atherosclerosis." (PMID 37947606, 2023). "The cGAS-STING pathway is linked with cellular proliferation and phenotypic conversion of VSMC and enhances the progression of atherosclerosis plaque." (PMID 36465175, 2022). "Gene expression profiling of cGAS inhibition in macrophages successfully identified important biological processes and pathways specific to atherosclerosis." (PMID 33589571, 2021). "The research results herein indicate that cGAS is probably a novel clue for the development of atherosclerosis through the inflammatory signaling pathway." (PMID 33589571, 2021). "APOA1, the main protein of high-density lipoprotein (HDL) which shows protective effects on atherosclerosis, was increased when cGAS was inhibited." (PMID 33589571, 2021). "In atherosclerosis, mitochondrial stress in oxLDL-engulfed macrophages induces mtDNA leakage into the cytosol, activating the cGAS-STING pathway to drive type I interferon responses, which promote vascular smooth muscle cell (VSMC) senescence and plaque instability." (PMID 40943400, 2025). "Although further investigations are necessary to be certain of the causative role of DNA damage, our findings indicate that the accumulation of DSBs contributes to the pathogenesis of atherosclerosis by promoting proinflammatory responses via the cGAS-STING-IRF3 pathway." (PMID 37777633, 2023). "In conclusion, accumulated cytosolic DNA caused by cigarette smoke and the resultant activation of the cGAS-STING pathway may be a mechanism of atherosclerosis development." (PMID 36598778, 2023). "However, some studies have also shown that upregulation of the cGAS-STING pathway leads to aggravation of atherosclerosis and NAFLD." (PMID 37762143, 2023).
atherosclerosis (continued). "Although cGAS acts mainly as a DNA sensor and the role in broadly eliciting immune responses and inflammation has also been reported, whether cGAS contributes to atherosclerosis is yet to be uncovered." (PMID 33589571, 2021). "This study focused on identifying the role of cGAS in atherosclerosis and its potential mechanisms." (PMID 33589571, 2021). "Accordingly, cGAS may act as a critical molecule for the development of atherosclerosis via an inflammatory response mediated by macrophages." (PMID 33589571, 2021). "Hypothetically therefore, cGAS may play a pivotal role in the development of atherosclerosis." (PMID 33589571, 2021). "In conclusion, cGAS may contribute to the development of atherosclerosis." (PMID 33589571, 2021). "These imply that cGAS may regulate atherosclerosis through macrophages." (PMID 33589571, 2021). "Our findings were similar to the results of other studies that focused on the function of cGAS-STING in regulating other inflammatory diseases, such as neuroinflammation, atherosclerosis, vascular inflammation and enteritis." (PMID 38491517, 2024). "Recent research has shown enhanced expression of GSDMD in atherosclerosis, where it can mediate the cGAS/STING/TBK1/IRF3/NF-κB signaling pathway, contributing to the process of atherosclerosis." (PMID 39301029, 2024). "The dysregulation of the cGAS-STING pathway in vascular inflammation isimplicated in various cardiovascular diseases, including atherosclerosis,hypertension, and vascular injury." (PMID 39076568, 2024). "Thus, the cGAS-STING-IRF3 axis may be a promising therapeutic target for atherosclerosis." (PMID 37777633, 2023). "During the activation of cGAS-STING, dissociated STIM1 from STING promotes atherogenesis and the development of atherosclerosis." (PMID 36465175, 2022). "In this study, we discover the connection between cGAS and TDP43 in AS development and firstly demonstrate that TDP43 functions as the upstream regulator of cGAS-triggered inflammation in atherosclerosis through inducing mitochondrial DNA release." (PMID 34291051, 2021). "cGAS―STING―PERK―IRF3/NF-κB―vascular endothelial dysfunction and atherosclerosis." (PMID 41153813, 2025). "The dysregulation of the cGAS-STING pathway in endothelial cells can contributeto endothelial dysfunction, a crucial step in the development and progression ofcardiovascular diseases such as atherosclerosis, hypertension, and vascularinflammation." (PMID 39076568, 2024). "In cardiovascular diseases, the release of mtDNA directly triggers cGAS-STING activation in vascular endothelial cells, while also recruiting immune cell infiltration and promoting cell polarization, This process exacerbates vasculitis, atherosclerosis and cardiac dysfunction." (PMID 41153813, 2025). "In order to have a better view of the mechanisms of atherosclerosis mediated by cGAS, we performed RNA-seq transcriptomic analysis of the underlying DEGs and the mechanisms in RAW264.7 macrophages treated for 12 h with or without RU.521, a cGAS inhibitor." (PMID 33589571, 2021). "Overexpression of IFN-I through the activation of TLR7/9 signal decreases the number and function of EPCs and increases atherosclerotic lesions in SLE patients, suggesting that targeted therapy of cGAS and RIG-I signal pathway may have a potential therapeutic effect on SLE atherosclerosis." (PMID 33262760, 2020).
pancreatic cancer (28 papers, 2020 to 2026). "Overall, these data support that, in addition to synthetic lethality between POLQ and BRCA2, cytosolic DNA damage products that accumulate in the presence of POLQ inhibition activate cGAS-STING signaling in BRCA2-deficient pancreatic cancer cells." (PMID 36976649, 2023). "Taken together, our data suggest that the cGAS–STING pathway plays a minor role in the susceptibility of pancreatic cancer cell lines to C-REV infection." (PMID 34203706, 2021). "Recent work has shown that deficiency of ATM and activation of cGAS-STING pathway improve the immune checkpoint blockade responses in pancreatic cancer by stimulating type I IFN." (PMID 34858438, 2021). "Further, we show that POLQ inhibition causes the accumulation of cytosolic DNA to activate the cyclic GMP-AMP synthase–stimulator of interferon genes (cGAS-STING) signaling pathway in BRCA2-deficient pancreatic tumors, thus enhancing intratumoral T cell infiltration." (PMID 36976649, 2023). "Thus, we demonstrate for the first time that POLQ is a promising target in HR-deficient pancreatic cancer and its role in eliciting cGAS-STING signaling." (PMID 36976649, 2023). "Pancreatic cancer data were retrieved from GEO and TCGA databases, the molecular subtypes of pancreatic cancer were determined using the six cGAS-STING related pathways, and the clinical phenotype, mutation, immunological characteristics and pathways related to pancreatic cancer were evaluated." (PMID 37547756, 2023). "We also observed increased cytosolic micronuclei formation in HR-deficient pancreatic cancer cells with POLQ inhibition and subsequent activation of the cGAS-STING pathway." (PMID 36976649, 2023). "We found that all tested pancreatic cancer cell lines maintained highly expressed cGAS, but STING was significantly downregulated in many of the PDAC cell lines and tissues." (PMID 36498833, 2022). "CGAS mRNA levels were higher in pancreatic cancer, HNSCC, and esophageal cancer cell lines compared with other solid tumor cell lines." (PMID 35563740, 2022). "In this paper, we show that there is little correlation between levels of cGAS/STING expression and susceptibility to C-REV among human pancreatic cancer cell lines." (PMID 34203706, 2021). "Multiple studies reported that DNA damage sensing by cGAS/STING pathway was critical in pancreatic cancer and NSCLC." (PMID 33858512, 2021). "Additional studies will be required to delineate the possible effects of the cGAS-STING pathway on other types of cell death in pancreatic tumors." (PMID 34858438, 2021). "Lastly, with pre-clinical evidence that immune signaling through the cGAS/STING pathway promotes HRD, it is possible that STING agonists could synergize with PARPis in both BRCA- and PALB2-mutated as well as wild-type pancreatic tumors." (PMID 40426860, 2025). "Furthermore, ATM inhibition was reported to activate TBK1 in a cGAS-STING-independent manner via SRC kinase in pancreatic cancer cells." (PMID 38084916, 2024). "We interrogated whether a similar cooperation could be witnessed in other cell lines, using THP‐1, but also the CFPAC pancreatic cancer cell line, and their cGAS−/− counterparts." (PMID 36574362, 2023). "Dr Tang’s group recently discovered that DNA damage (mitochondrial DNA and nuclear DNA) induced by cathepsin B nuclear translocation or zalcitabine/erastin-induced mitochondrial stress activates cGAS-STING to trigger autophagy-dependent ferroptosis of pancreatic cancer cells." (PMID 35902564, 2022). "Therefore, we next analyzed the expression of cGAS mRNA in the tumor tissues of pancreatic cancer, HNSCC, and esophageal cancer and adjacent normal tissues using Cancer RNA-Seq Nexus." (PMID 35563740, 2022). "Therefore, the role of the cGAS-STING pathway in pancreatic cancer worth an in-depth study." (PMID 37547756, 2023). "Using data from public databases, we highlighted the significance of the cGAS-STING pathway in CCA and pancreatic cancer." (PMID 40786100, 2025).
pancreatic cancer (continued). "GEPIA analysis revealed that members of the cGAS-STING pathway were significantly increased in GI cancers, particularly CCA and pancreatic cancer." (PMID 40786100, 2025). "Our findings revealed that D166 activated the cGAS-STING pathway in a time- and dose-dependent manner in patient-derived pancreatic tumor organoid models." (PMID 40520004, 2025). "Dronedarone hydrochloride (DH) has been shown to increase mitochondrial stress in pancreatic cancer, leading to mitochondrial DNA (mtDNA) leakage and activation of the cGAS-STING pathway, thereby inducing pyroptosis in pancreatic cancer cells." (PMID 39994107, 2025). "D166 demonstrated a time- and dose-dependent effect in activating the cGAS-STING pathway and inducing IFN-β in pancreatic cancer organoids." (PMID 40520004, 2025). "Next, we knocked down STING expression in pancreatic cancer organoids and added the TBK1 inhibitor MRT67037 to confirm whether D166 exerts its tumor-killing effects through the cGAS-STING pathway." (PMID 40520004, 2025). "A recent pancreatic cancer OV screen showed that tumor-intrinsic antiviral defenses strongly influence efficacy: high interferon-stimulated gene expression correlated with resistance, whereas impaired IFN signaling (e.g., low cGAS/STING activity) enhanced sensitivity." (PMID 41440025, 2025). "We found that enhanced T1IFN expression by ATM inhibitor in combination with radiation was mediated by the POLIII/RIG-I/MAVS signaling pathway, independent of the canonical cGAS/STING pathway, suggesting the potential dysregulation of cGAS/STING signaling in pancreatic cancer." (PMID 38376927, 2024).
gastric cancer (27 papers, 2020 to 2026). A primary or metastatic malignant neoplasm involving the stomach. "The research focuses on HER-2’s role in cancer (especially breast and gastric cancer), its association with prognosis and treatment responses, and its impact on other signaling pathways like the cGAS-STING pathway or inflammation." (PMID 41304707, 2025). "This association hints at the possibility that the cGAS-STING pathway is involved in activation of the immune response against gastric cancer cells." (PMID 39050748, 2024). "This review outlines the expression of cGAS-STING in gastric cancer and its association with key genetic markers related to gastric cancer, elucidating its potential therapeutic implications in this context." (PMID 39063990, 2024). "Therefore, our data suggested that TRIM6 triggers the proteasomal degradation of cGAS via K27-linked polyubiquitination and negatively regulates cGAS abundance in gastric cancer cells." (PMID 40817248, 2025). "Moreover, a predictive model based on cGAS-STING pathway-associated genes (CSRs) was developed to forecast overall survival in gastric cancer patients using bioinformatics techniques applied to The Cancer Genome Atlas (TCGA) and Gene Expression Omnibus (GEO) databases." (PMID 39063990, 2024). "Trim6 depletion in immunologically ‘cold’ MSS gastric cancer cells promotes CD8+ T-cell infiltration by activating the cGAS-mediated innate immune response and sensitizes these tumors to anti-PD-1/PD-L1 treatment." (PMID 40817248, 2025). "Here, we demonstrated that the RING E3 ligase TRIM6 can degrade cGAS via K27-linked polyubiquitination and impair cGAS-STING signaling in gastric cancer." (PMID 40817248, 2025). "This study investigates the role of 2’-5’ oligoadenylate synthetase-like (OASL) in Oxaliplatin (OXA)-induced immunogenic cell death (ICD) in Gastric cancer (GC) cells through the cGAS-STING signaling pathway." (PMID 41271618, 2025). "Activating the cGAS‐STING signaling pathway suppresses gastric cancer cell proliferation, migration, and immune evasion." (PMID 39834553, 2025). "The anti‐tumor drug anlotinib can inhibit gastric cancer cell proliferation, migration, and immune escape by activating the cGAS‐STING signaling pathway." (PMID 39834553, 2025). "Differential expression of a multitude of cGAS-STING pathway-related genes (CSRs) was discovered in cancerous tissue in patients with gastric cancer." (PMID 39050748, 2024). "Due to the role of cGAS in recognizing pathogen-derived DNA and the extensive foreign pathogens and inflammatory exposures that lead to gastric cancer, studying the role of cGAS in gastric cancer has become an important area of investigation." (PMID 39050748, 2024). "cGAS KO gastric cancer shows decreased tumor cell viability. cGAS KO mice show lower tumor burden and growth. cGAS over-expression in AGS cells leads to activation of the MRN complex, promoting genomic instability." (PMID 39050748, 2024). "A recent investigation has revealed that the expression of five genes linked to the cGAS-STING pathway, namely IFNB1, IFNA4, IL6, NFKB2, and TRIM25, exhibits potential as a valuable prognostic marker for OS in patients suffering from gastric cancer." (PMID 38240703, 2024). "In the context of gastric cancer, harnessing the cGAS-STING pathway holds significant potential for biotherapeutic interventions." (PMID 39063990, 2024). "Similar to its dichotomous role in esophageal cancer, cGAS influences cancer immunity and progression within gastric cancer cells." (PMID 39050748, 2024). "This review provides a comprehensive overview of the latest research on cGAS-STING in gastric cancer, including insights from clinical trials involving STING agonists." (PMID 39063990, 2024). "The application of nanocomposites to simultaneously target mitochondrial and nuclear DNA results in an increased cGAS-mediated upregulation of innate immunity and an influx of tumor-infiltrating lymphocytes in gastric cancer." (PMID 39050748, 2024).